LRP1 (LDL receptor related protein 1)
Diseases named in the same sentence as LRP1 in open-access papers (continued):
Sharing a sentence is not in itself a finding about the gene and the disease.
brain inflammation (1 paper, 2021). "The current study revealed that the LRP1 NPxY mutation also reduces HFHC diet-induced brain inflammation." (PMID 33500241, 2021).
brain trauma (1 paper, 2013). "Recently the action of the t-PA-PAI-1 complex was shown an inducer of a MMP cascade through LRP-1 activation in brain trauma resulting in vascular permeability and oedema." (PMID 23940734, 2013).
bunyavirus infections (1 paper, 2025). "Some studies suggest that Lrp1 not only acts as a receptor for RVFV but also as a key cell surface factor mediating OROV invasion, indicating the widespread importance of Lrp1 in various bunyavirus infections." (PMID 39942606, 2025).
chronic asthma (1 paper, 2025). An asthma that is characterized by the development of persistent airway inflammation and recurrent attacks of breathlessness and wheezing, which vary in severity and frequency. "To verify the critical role of LRP1 in ASM proliferation in chronic asthma in vivo, we administered intratracheal instillations of lentivirus containing Lrp1 shRNA or NC shRNA to OVA-challenged mice." (PMID 40338656, 2025). "In summary, our results indicated that LRP1 was upregulated in ASM cells of mice with OVA-induced chronic asthma and that this upregulated LRP1 promoted ASM cell proliferation by activating the FGF2/ERK signaling pathway." (PMID 40338656, 2025). "In the present study, LRP1 was increased in ASM cells of mice with OVA-induced chronic asthma, with the elevation in LRP1-ICD protein levels being significantly greater than that of the LRP1 β chain." (PMID 40338656, 2025). "In the current study, we first identified an upregulation of LRP1 in airway tissues of mice with OVA-induced chronic asthma and found a significantly greater increase in LRP1-ICD protein levels compared with the LRP1 β chain." (PMID 40338656, 2025). "Overall, these key findings suggest that LRP1 may promote ASM proliferation in mice with OVA-induced chronic asthma by activating the FGF2/ERK signaling pathway." (PMID 40338656, 2025). "Upregulation of LRP1 expression in ASM cells of mice modeling chronic asthma induced by OVA." (PMID 40338656, 2025). "Lrp1 knockdown attenuates ASM proliferation in mice with OVA-induced chronic asthma." (PMID 40338656, 2025).
colitis (1 paper, 2025). Inflammation of the colon. "While LRP1 serves as a novel APOA4 receptor in adipose tissue for glucose homeostasis, it remains to be determined whether APOA4-LRP1 interactions in the intestine can similarly suppress inflammatory cytokine production and restrict the development of colitis or IBD." (PMID 40723884, 2025).
dengue disease (1 paper, 2024). Dengue fever (DF), caused by dengue virus, is an arboviral disease characterized by an initial non-specific febrile illness that can sometimes progress to more severe forms manifesting capillary leakage and hemorrhage (dengue hemorrhagic fever, or DHF) and shock (dengue shock syndrome, or DSS). "Hence, this result associates LRP1 with the viral interference phenomenon, which, in light of our findings regarding the direct interaction with DENV virions, reinforces the notion that LRP1 is directly linked to the process of DENV infection in vivo and the pathogenesis of dengue disease." (PMID 39599807, 2024).
dyslipidaemia (1 paper, 2021). "We detected an inverse correlation between sLRP-1 levels and markers of dyslipidaemia suggesting that the suppression of LRP-1 levels induced by free fatty acids was stronger than the shedding effect of atherogenic lipids." (PMID 33916750, 2021). "Inactivation of hepatic LRP-1 gene in mice resulted in decreased cholesterol-rich remnant lipoproteins clearance with consequential accumulation of these lipoproteins in the circulation, implicating that dyslipidaemia could be not only the reason for but the consequence of low LRP-1 levels." (PMID 33916750, 2021).
Flavivirus Infections (1 paper, 2019). Infections with viruses of the genus FLAVIVIRUS, family FLAVIVIRIDAE. "Accordingly, stimuli that are present during flavivirus infection reduced LRP-1 protein expression." (PMID 31015516, 2019).
gestational diabetes (1 paper, 2021). Carbohydrate intolerance first diagnosed during pregnancy. "Our results highlight an increased expression of LRP1 and LPL in placentas of insulin-treated gestational diabetes and, in turn, an increase in the intracellular ROH apparatus by the non-STRA6 pathway." (PMID 34945773, 2021).
glomerular diseases (1 paper, 2011). "Hence, LRP1 represents a promising new therapeutic target for the control of proliferative glomerular diseases." (PMID 21445358, 2011).
gout (1 paper, 2020). A condition characterized by painful swelling of the joints, which is caused by deposition of urate crystals. "Certainly these results support further continued research about the role of LRP1 and OIT3 in gout susceptibility." (PMID 32569156, 2020). "Other studies have provided evidence for the role that LRP1 plays in gout." (PMID 32569156, 2020). "The rare occurrence of the 2 sequence variants associated with gout within a single family and the inheritance pattern over 5 generations within that family provide both support and potential insight about the relevance of LRP1(rs767716691) and OIT3(rs554643826) to gout." (PMID 32569156, 2020). "It is possible these 2 mutations of low-density lipoprotein receptor-related protein 1 (LRP1) and oncoprotein induced transcript 3 (OIT3) could contribute to the development of gout in the direct descendants." (PMID 32569156, 2020). "Two rare, highly detrimental variants, LRP1(rs767716691) and OIT3(rs554643826) were detected in 6 direct descendants, although 1 of the 6 descendants (IV-3) has not been diagnosed with gout." (PMID 32569156, 2020). "The rare sequence variants in low-density lipoprotein receptor-related protein 1 (LRP1) and oncoprotein induced transcript 3 (OIT3) may have contributed to inheritance of gout within the 5 generations of family members in this study." (PMID 32569156, 2020).
gram-negative bacterial infections (1 paper, 2020). Infections caused by bacteria that show up as pink (negative) when treated by the gram-staining method. "LRP1 inhibition leads to an enhanced sensitivity to lipopolysaccharide (LPS), a stimulus of Gram-negative bacterial infections, activating the production of pro-inflammatory cytokines through NK-kB and JNK pathways." (PMID 33391288, 2020).
HCMV infection (1 paper, 2025). "LRP1 expression increases during HCMV infection, reducing viral cholesterol and infectivity." (PMID 41244697, 2025). "The increased expression of LRP1 may be a defensive response to HCMV infection, suggesting that LRP1 limits the infectivity of HCMV." (PMID 41244697, 2025).
head and neck squamous cell carcinoma (1 paper, 2017). A squamous cell carcinoma that arises from any of the following anatomic sites: lip and oral cavity, nasal cavity, paranasal sinuses, pharynx, larynx, and salivary glands. "Using PCR and quantitative PCR, the expression of LRP1 and smLRP1 in different human tissues and tumour cell lines was screened and compared on tumour biopsies of head and neck squamous cell carcinoma (HNSCC)." (PMID 28662213, 2017).
hemiplegic migraine (1 paper, 2025). "This study presents novel evidence linking hemiplegic migraine (HM) to rare variants in genes previously implicated in cerebral SVD, including LRP1, COL4A1, and TGFBR2." (PMID 40869943, 2025).
hypercoagulability (1 paper, 2021). "Taken together, decreased levels of LRP-1 may have an association with the OSA-related hypercoagulability." (PMID 33916750, 2021). "Thus, the dysregulation of the LRP-1 pathway could contribute to the metabolic and inflammatory changes as well as to hypercoagulability seen in OSA." (PMID 33916750, 2021).
infarction (1 paper, 2025). A localised pathological necrosis of tissue resulting from obstruction of the blood supply usually by a thrombus, an embolus, or vascular torsion. "For instance, the synthesized LRP1 agonist (SP16) has been found to rapidly induce Akt phosphorylation, exert anti-inflammatory effects, and inhibit programmed death of myocardial cells, thereby protecting the surviving myocardium adjacent to the infarction scar." (PMID 40083817, 2025).
inner ear disorder (1 paper, 2022). A non-neoplastic or neoplastic disorder affecting the inner ear. "Considering the severe situation of inner ear disorders worldwide, the discovery of the transporting receptor LRP1 may play crucial roles in treating inner ear disorders in the future." (PMID 35680846, 2022). "The discovery of the receptor LRP1 will illuminate developing strategies for crossing the BLB and for improving systemic drug delivery for inner ear disorders." (PMID 35680846, 2022). "Currently, the presence of the BLB impedes the systemic drug administration of drugs to the inner ear, while the discovery of LRP1 and its ligand IETP2 may provide a new avenue for noninvasive and systemic administration that is feasible for patients with inner ear disorders." (PMID 35680846, 2022).
intracerebral hemorrhage (1 paper, 2022). A cerebrovascular disorder characterized by bleeding into one or both cerebral hemispheres including the basal ganglia and the cerebral cortex. "Low-density lipoprotein receptor-related protein-1 (LRP1) can exert strong neuroprotection in experimental intracerebral hemorrhage." (PMID 36035210, 2022).
intracranial aneurysms (1 paper, 2017). "The association between LRP1 and intracranial aneurysms has to our knowledge not been studied yet." (PMID 28523215, 2017).
invasive carcinoma (1 paper, 2021). A carcinoma that is not confined to the epithelium, and has spread to the surrounding stroma. "Loss of LRP‐1 in CHO‐K1 cells leads to transformation into carcinoma cells (CHO‐LRP‐1−/− cells) which exhibited a spindle‐shaped fibroblastoid morphology, frequently observed in invasive carcinoma cells." (PMID 34485840, 2021).
iron deficiency (1 paper, 2026). "Although Hmox1 was not upregulated, several heme-scavenging genes (Hpx, Lrp1/Cd91) were induced, while others involved in heme or biliverdin handling (Slc48a1/Hrg1, Pgrmc1, Blvrb) were downregulated, suggesting a compensatory shift in heme-related processes consistent with iron deficiency." (PMID 41598416, 2026).
joint diseases (1 paper, 2020). "Further research will investigate the presence of LRP-1 in human articular cartilage, whether it is measurable extracellularly, and whether it is able to assess disease progression and distinguish between OA and other joint diseases." (PMID 32586320, 2020).
Listeria infection (1 paper, 2016).
lymph node metastasis (1 paper, 2023). "Logistic regression analysis confirmed that high LRP1 expression was more commonly found in high-grade non-papillary BLCA, and high LRP1 expression levels increased the risk of advanced T stage (p<0.001) and lymph node metastasis (p=0.004)." (PMID 37153545, 2023).
MELAS (1 paper, 2019). "Instead, the expression of low-density lipoprotein receptor-related protein 1 (LRP1), a receptor involved in receptor-mediated endocytosis, was found to be highly upregulated in MELAS ECs." (PMID 31641105, 2019).
neurotoxicity (1 paper, 2022). Toxicity that causes injury to the central or peripheral nervous system or damages its function. "The third module included 3 genes in Neurotoxicity (Itpr1, Trim8, Lrp1), 4 in Blood–brain barrier (Ptpn23, Claudin5, Plectin, Mmp2) and 4 in Cognitive function (Slc8a3, Srf, Nf1, Ncam1)." (PMID 35899365, 2022).
ocular infection (1 paper, 2022). "Although this was validated in cell lines of taxonomically different species, including BCE cells, the role of Lrp1 in human ocular infection is unclear." (PMID 36194021, 2022).
pancreatic adenocarcinoma (1 paper, 2022). "In addition, high levels of low-density lipoprotein receptor-related protein 1 (LRP1) were associated with worsened patient survival in pancreatic adenocarcinoma." (PMID 35628341, 2022).
peroxisome biogenesis disorder (1 paper, 2017). "Because PEX2 has been implicated in peroxisome biogenesis, and peroxisome biogenesis disorders (PBDs) are typically associated with impaired lipid metabolism and CNS myelin defects, this prompted us to further explore a potential link between LRP1 and peroxisomes." (PMID 29251594, 2017).
poisoning (1 paper, 2020). A condition or physical state produced by the ingestion, injection, inhalation of or exposure to a deleterious agent. "To probe the possible role of the LRP1 receptor in ricin-mediated pulmonary poisoning, we tested the contribution of LRP1 to ricin intoxication in a single cell suspension produced from mice lungs." (PMID 32488096, 2020).
prediabetes (1 paper, 2023). "Results from the present study show that the cardiac LRP1-ANP axis previously reported by our group in an experimental murine model of prediabetes is likely working in T2DM patients." (PMID 37635956, 2023).
preeclampsia (1 paper, 2023). Preeclampsia is a hypertensive disorder of pregnancy that is characterized by new-onset hypertension with proteinuria presenting after 20 weeks of gestation, and depending on mild or severe forms may initially present with severe headache, visual disturbances, and hyperreflexia. "In addition, these genes were elevated in the placentas of preeclampsia patients, including LRP1, COL6A1, ITGB2, and MMP3." (PMID 38003549, 2023).
prostate tumour (1 paper, 2017). "Interestingly, the expression ratio of smLRP1 relative to LRP1 was found to shift in tumour cell lines of brain, lung, colon, and prostate tumour towards higher smLRP1 levels and decreased in HNSCC cell." (PMID 28662213, 2017).
rectal cancer (1 paper, 2022). A primary or metastatic malignant neoplasm that affects the rectum. "LRP-1 or survivin may have a specific association with radiotherapy tolerance in rectal cancer, and targeted inhibition of LRP-1 or survivin can improve the prognosis of patients." (PMID 36106114, 2022). "Low-density lipoprotein receptor-related protein-1 (LRP-1) and survivin are associated with radiotherapy resistance in patients with locally advanced rectal cancer (LARC)." (PMID 36106114, 2022). "A previous study has shown that patients with high LRP-1 expression who were subjected to radiotherapy had a poor prognosis, implying that LRP-1 could be an important marker for discriminating radioresistant rectal cancer." (PMID 36106114, 2022).
renal fibrosis (1 paper, 2024). A final common manifestation of a wide variety of chronic kidney diseases characterized by glomerulosclerosis and tubulointerstitial fibrosis. "Treml4_Mono and Fn1_Mac expressed a variety of similar chemokines, such as Csf1r, Lrp1, Ccl6, and Tgfb1, and the latter protein promoted early repair but was involved in renal fibrosis during the progression of AKI-CKD." (PMID 38258908, 2024).
retinal disease (1 paper, 2021). "Our approach used WES to identify novel genes in IRDs and through this work we have identified two putatively novel associations in retinal disease: LRP1 in drusen formation and UBE2U in a novel syndrome." (PMID 33776059, 2021).
sandfly fever (1 paper, 2023). "In the human cell line HuH-7, LRP1 also promoted early infection stages of sandfly fever Sicilian virus and La Crosse virus, but had a minor effect on late infection by vesicular stomatitis virus, whereas encephalomyocarditis virus was entirely LRP1-independent." (PMID 37072184, 2023).
silicosis (1 paper, 2024). Silicosis is a respiratory disease caused by breathing in (inhaling) silica dust. "The Fibr-2 macrophage subset likely represents end-stage profibrotic macrophages in the silicosis lung due to waning expression of profibrotic genes coupled with increased expression of foamy macrophage markers including Spp1, Cd36, and lipid-metabolizing genes such as Lgals3 and Lrp1." (PMID 38985878, 2024).
Type 1 von Willebrand disease (1 paper, 2025). "Type 1 von Willebrand disease (VWD) is often caused by variants in von Willebrand factor (VWF), including p.R1205H (“Vicenza mutation”), which accelerate VWF clearance via macrophage receptor LRP1 and impair platelet adhesion and activation." (PMID 41337046, 2025).
urothelial carcinoma (1 paper, 2017). A malignant neoplasm derived from the transitional epithelium of the urinary tract (urinary bladder, ureter, urethra, or renal pelvis). "The correlation between LRP1 mRNA expression and patient survival in urothelial carcinoma was unanticipated because LRP1 mRNA expression was relatively low in this cancer compared with other malignancies." (PMID 29088295, 2017).
Venous thrombosis (1 paper, 2024). Formation of a blood clot (thrombus) inside a vein, causing the obstruction of blood flow. "In accordance, rosuvastatin showed anticoagulant effect in patients with venous thrombosis by increasing LRP1 expression both in vitro and in vivo and high dose rosuvastatin was required to increase ABCA1 transporter in human atherosclerotic plaques." (PMID 39708240, 2024).
Vestibular schwannoma (1 paper, 2025). A vestibular schwannoma (also known as acoustic neuroma, acoustic neurinoma, or acoustic neurilemoma) is a benign, usually slow-growing tumor that develops from the VIIIth cranial nerve supplying the inner ear. "Our cell communication analysis based on the curated receptor-ligand pair database showed that fibroblast in vestibular schwannoma microenvironment mainly regulated the biological behavior of tumor cells through PSAP/GPR37L1, MDK/(ITGA6 + ITGB1), IGF2/(ITGA6 + ) and MDK/LRP1 signaling axes." (PMID 40629113, 2025).
vitiligo (1 paper, 2023). Generalized well circumscribed patches of leukoderma that are generally distributed over symmetric body locations and is due to autoimmune destruction of melanocytes. "A high expression of LRP1, among other factors such as environmental conditions, may determine an individual’s susceptibility to vitiligo." (PMID 37020553, 2023). "An increased expression of LRP1 is observed in monocytes of vitiligo patients, when compared with healthy controls." (PMID 37020553, 2023). "A high LRP1 expression in active vitiligo patients suggests that LRP1 may play a significant role in vitiligo progression and thus LRP1 represents a potential target for novel therapeutic approaches to modulate this autoimmune condition." (PMID 37020553, 2023).